HOOK1 (hook microtubule tethering protein 1)
Diseases named in the same sentence as HOOK1 in open-access papers:
HOOK1 is named in the same sentence as 41 diseases in open-access papers, as found by Europe PMC text mining. Sharing a sentence is not in itself a finding about the gene and the disease. The quoted sentences say what the papers report.
breast carcinoma (3 papers, 2016 to 2023). "HOOK1 (up-regulated 96-fold) interacts with microtubules and is up-regulated in breast cancer." (PMID 26847345, 2016).
colon cancer (2 papers, 2014 to 2023). "Hook1 is down-regulated in colon cancer cells by inducible expression of hSnaill." (PMID 25331952, 2014).
endometriosis (2 papers, 2023 to 2024). The growth of functional endometrial tissue in anatomic sites outside the uterine body. "HOOK1 is strongly associated with M2 macrophages in endometriosis, and GBP5 is associated with a high infiltration of B-cells, CD4+ T-cells, CD8+ T-cells, and NK-cells in small cell lung cancer." (PMID 38384272, 2024). "Our findings suggest that MYO6 and HOOK1 are associated with immune infiltration in endometriosis and can be used as novel potential biomarkers and predictors of immune cell infiltration in endometriosis." (PMID 37817158, 2023). "The immunohistochemical result indicated that the protein levels of MYO6 and HOOK1 were increased in patients with endometriosis, further suggesting that MYO6 and HOOK1 can be used as potential biomarkers for endometriosis." (PMID 37817158, 2023). "MYO6 and HOOK1 can be used as potential biomarkers for endometriosis." (PMID 37817158, 2023). "MYO6 and HOOK1 have a limited impact on the immune system in endometriosis." (PMID 37817158, 2023). "The difference in the results of dataset GSE7305 demonstrated that all NRDEGs were statistically significant, and the expression levels of C7, HOOK1, PKP3, AHR, GJB1, and MYO6 in different groups of endometriosis dataset GSE7305 were statistically significant (P < 0.001)." (PMID 37817158, 2023).
hepatocellular carcinoma (2 papers, 2020 to 2023). A malignant tumor that arises from hepatocytes. "It was recently reported that Hook1 inhibits malignancy and EMT in several cancer types, including hepatocellular carcinoma, thyroid cancer and non-small-cell lung cancer." (PMID 32156068, 2020).
infertile (2 papers, 2019 to 2022). "Investigations in male mice have found that loss-of-function mutations in genes involved in the production of headless spermatozoa, such as Spata6, Hook1, Prss21, Oaz3, and Odf1, can cause fertility reduction or infertility." (PMID 36028792, 2022).
ovarian carcinoma (2 papers, 2023 to 2024). A malignant neoplasm originating from the surface ovarian epithelium. "In both ovarian cancer cell lines, we observed that downregulating HOOK1 caused a decrease in the percentage of EpCAM + cells compared to that of parental cells." (PMID 38807192, 2024). "Our data provide evidence that reducing HOOK1 leads to a decrease in cancer stem-like properties in ovarian cancer cells." (PMID 38807192, 2024). "For this purpose, we decreased HOOK1 levels in ovarian cancer cell lines and observed that this reduction affects their proliferative and survival capabilities." (PMID 38807192, 2024). "In this study, we characterized the importance of HOOK1 for the aggressive phenotype of ovarian cancer." (PMID 38807192, 2024). "In this study, we observed that reducing the levels of HOOK1 in ovarian cancer cells reduced in vitro growth and migration and prevented tumor formation in vivo." (PMID 38807192, 2024). "The downregulation of HOOK1 in ovarian cancer cell lines has resulted in a decrease in their tumorigenic and stemness properties while significantly increasing cell death." (PMID 38807192, 2024). "In summary, HOOK1 is involved in the maintenance of ovarian cancer cell growth and migration, and its downregulation negatively impacts these cells, causing a significant increase in cell death and preventing the formation of tumors in vivo." (PMID 38807192, 2024). "The downregulation of HOOK1 was performed in ovarian cancer cell lines using CRISPR/Cas9 technology, followed by growth in vitro and in vivo assays." (PMID 38807192, 2024). "Immunofluorescence staining, Western-blotting and flow cytometry were also employed to finish uncovering the role of HOOK1 in ovarian cancer." (PMID 38807192, 2024). "Therefore, overall, the reduction in HOOK1 levels seems to sensitize ovarian cancer cells to both ER stress-inducing drugs and proteasome inhibitors." (PMID 38807192, 2024). "Thus, it appears that the reduction in HOOK1 increases the activation of the apoptotic pathway in ovarian cancer cells and leads to an increase in cell death, both through apoptosis-dependent and apoptosis-independent mechanisms." (PMID 38807192, 2024). "Altogether, the activation of UPR signaling observed through both WB analysis and proteomics, along with the heightened sensitivity to these drugs, provides solid confirmation of the elevated ER stress levels in ovarian cancer cell lines when HOOK1 levels are reduced." (PMID 38807192, 2024). "Consequently, we investigated whether the decrease in HOOK1 could sensitize ovarian cancer cells to ER stress-inducing agents." (PMID 38807192, 2024). "Therefore, it would be interesting to study HOOK1 inhibition as a potential treatment for ovarian cancer, either as monotherapy or in combination with chemotherapeutic agents or other drugs inducing proteotoxic stress, such as inhibitors of the proteasome or promoters of the UPR response." (PMID 38807192, 2024). "Additionally, we studied whether HOOK1 could affect the survival of ovarian cancer cells." (PMID 38807192, 2024). "Therefore, the involvement of HOOK1 in diminishing stem properties in ovarian cancer cells seems to be independent of the expression of these genes conventionally linked to stemness, suggesting the presence of an alternative mechanism to account for such alterations." (PMID 38807192, 2024).
teratozoospermia (2 papers, 2019 to 2022). "HOOK1 is suggested as a candidate for decapitation defects and teratozoospermia." (PMID 35286314, 2022).
acephalic spermatozoa syndrome (1 paper, 2021). "BRDT, DNAH6, CEP112, and HOOK1 have also been reported to be associated with acephalic spermatozoa syndrome." (PMID 34422805, 2021).
carcinoma of renal pelvis (1 paper, 2023). "We analyzed CheckMate 025(CM‐025) (phase 3 trial of anti‐PD‐1 in 180 advanced RCC) and IMvigor210(IV‐210) (Phase 2 study investigating anti‐PD‐L1 in metastatic urothelial cancer, including 66 carcinoma of renal pelvis) data to test whether HOOK1 enhanced anti‐tumor immunity." (PMID 37085921, 2023).
Cognitive impairment (1 paper, 2016). Abnormal cognition is characterized by deficits in thinking, reasoning, or remembering. "Furthermore, patient DCP300407 with only HOOK1, CYP2J2 and C1orf87 deleted displays cognitive impairment." (PMID 26997977, 2016).
dementia (1 paper, 2016). Loss of intellectual abilities interfering with an individual's social and occupational functions. "While HOOK1 interacts with CLN3, the causative gene for the autosomal recessive Batten disease characterized by visual impairment, gait anomalies, seizures, dementia and sometimes mental deterioration, DNAJC6 has been shown to be implicated in Parkinson disease." (PMID 26997977, 2016).
Ewing sarcoma (1 paper, 2019). A small round cell tumor that lacks morphologic, immunohistochemical, and electron microscopic evidence of neuroectodermal differentiation. "Notably, on this list, we observed both well-established and candidate oncogenes in Ewing sarcoma, with many of which displayed striking Ewing sarcoma-specific expression profiles (e.g. LINGO1, HOOK1, CITED2 and IGF2BP1)." (PMID 30496486, 2019).
Intellectual disability (1 paper, 2016). "We propose six candidate genes (DAB1, HOOK1, DOCK7, DNAJC6, PDE4B, and NFIA) for the clinical features such as intellectual disability and OCD observed in DGDP005, because each of these genes is involved directly or indirectly in neurological disorders." (PMID 26997977, 2016). "We also determined the transcript levels of six candidate genes (DAB1, HOOK1, NFIA, DOCK7, DNAJC6 and PDE4B) for syndromic intellectual disability." (PMID 26997977, 2016). "Comparative deletion mapping showed that there are at least six candidate genes including, NFIA, HOOK1, DOCK7, DAB1, DNAJC6, and PDE4B, that could contribute to the syndromic or non-syndromic intellectual disability." (PMID 26997977, 2016).
leukemia (1 paper, 2013). A malignant (clonal) hematologic disorder, involving hematopoietic stem cells and characterized by the presence of primitive or atypical myeloid or lymphoid cells in the bone marrow and the blood. "Moreover, so far COSMIC has cataloged 28 HOOK1 somatic mutations in solid cancer tissues but none was previously found in leukemia." (PMID 24498620, 2013).
metastatic tumors (1 paper, 2023). "Moreover, GSEA analysis revealed that VEGF signaling pathway was significantly enriched in TNFSF13B‐higher tumors, and pan‐cancer analysis manifested that expression of HOOK1 was widely elevated in many cancers and metastatic tumors." (PMID 37085921, 2023).
ovarian tumors (1 paper, 2024). "In previous studies, HOOK1 has been suggested to be linked to platinum resistance in ovarian tumors." (PMID 38807192, 2024). "HOOK1 has been found to be transcriptionally altered in a substantial percentage of ovarian tumors, but its role in tumor initiation and development is still not fully understood." (PMID 38807192, 2024). "We observed that HOOK1 expression was significantly higher in ovarian tumors than in normal tissue and that the overall survival tends to be worse in tumors where this gene is highly expressed." (PMID 38807192, 2024). "Altogether, these data show that there is a high percentage of ovarian tumors with HOOK1 alterations and expression changes and that these modifications may be associated with a worse prognosis in patients." (PMID 38807192, 2024). "Due to the previously found physiological alterations, we wondered whether HOOK1 might also play a role in the generation or maintenance of CSCs in ovarian tumors." (PMID 38807192, 2024). "Therefore, HOOK1 seems to be important for the maintenance of ovarian tumors, and its inhibition could be a promising therapeutic strategy." (PMID 38807192, 2024). "Given that reducing HOOK1 levels leads to the occurrence of proteotoxic stress and compromises the survival of CSCs, inhibiting this protein could be a promising therapeutic strategy in ovarian tumors." (PMID 38807192, 2024).
Pancreatic cysts (1 paper, 2018). A cyst of the pancreas that possess a lining of mucous epithelium. "Two DEPs (HOOK1 and PTPN6) were validated by western blot using 19 pancreatic cyst fluid samples (10 LGD, 4 HGD, and 5 invasive IPMN)." (PMID 29713252, 2018).
renal carcinoma (1 paper, 2023). A carcinoma arising from the epithelium of the renal parenchyma or the renal pelvis. "Moreover, univariate and multivariate by Cox proportional hazard model was applied to determine the prognostic value of HOOK1 which showed that the high expression of HOOK1 was an independent predictor of better overall survival in patients with renal cancer." (PMID 37085921, 2023).
renal cell carcinoma (1 paper, 2023). "The findings reveal a pivotal role of HOOK1 in anti‐cancer treatment, and identify a novel therapeutic strategy for renal cell carcinoma." (PMID 37085921, 2023). "However, the clinicopathological and biological significance of HOOK1 in renal cell carcinoma (RCC) remains rarely studied." (PMID 37085921, 2023). "Together, our results demonstrated that the HOOK1 governed TNFSF13B stability and played a critical role in disease progression in renal cell carcinoma." (PMID 37085921, 2023).
renal tumors (1 paper, 2023). "Various fusion genes have been identified in recent years, such as VCL, TPM3, EML4, STRN, and HOOK1, with renal tumors of VCL and HOOK1 rearranged with ALK only described in pediatric patients." (PMID 37367052, 2023).
cancer (8 papers, 2014 to 2024). A tumor composed of atypical neoplastic, often pleomorphic cells that invade other tissues. "To investigate the mechanism of action of HOOK1 in cancer, we conducted a study of the proteome of cells with downregulated HOOK1." (PMID 38807192, 2024). "Hence, the precise role of HOOK1 in cancer and its underlying mechanism remain unclear." (PMID 38807192, 2024). "Meanwhile, we found E2F3 (transcription factor 3), which correlated with poor prognosis in a variety of cancers, was negatively regulated HOOK1 transcription though directly binding to the HOOK1 promoter by VHL dependent manner in RCC." (PMID 37085921, 2023). "As adhesion of tumor cells to the extracellular matrix is a key step in cancer metastasis, we then performed cell fibronectin adhesion assays and found HOOK1 significantly suppressed cell adhesion." (PMID 37085921, 2023). "What is more, pan‐cancer analysis showed HOOK1 was downregulated in most metastatic specimens." (PMID 37085921, 2023). "The dramatically decrease of HOOK1 in PDAC may suggest a molecular basis of aberrant EMT during cancer progression." (PMID 30598639, 2018). "Confirmation that Hook1 is negatively involved in the process of EMT suggests that it might be a potential target for interrupting EMT in cancer cell, which is important for metastasis." (PMID 25331952, 2014). "Nonetheless, the mechanism by which HOOK1 may be involved in cancer remains unclear." (PMID 38807192, 2024). "Based on the described use of drugs affecting proteostasis as therapeutic strategies in cancer, HOOK1 could be a promising therapeutic target, since reducing this protein affects multiple cellular processes capable of triggering proteotoxic stress in tumor cells." (PMID 38807192, 2024). "As expected, HOOK1 high expression group had a lower proportion of cancer‐associated fibroblasts (CAF), extracellular matrix (ECM) and pro‐inflammatory factors, and was associated with a lower EMT score, indicating HOOK1 enhanced antitumor activity via TME remodeling." (PMID 37085921, 2023). "On the contrary, we noted the role of GLO1, HOOK1, and GIPC2 was rarely investigated in CRC but well identified in other cancers." (PMID 36281556, 2023). "Consistent with the literature, the results of the present study showed fusion of the FGFR2 gene with nine different partners, namely, TACC2, BICC1, BTBD16, WAC, HFM1, HOOK1, INPP5F, C10orf90, and WDR11, in five different types of cancer." (PMID 35342406, 2022). "Other five genes, including BSPRY, C8ORF47, FAM3B, HOOK1 and REG1A, were clustered in Model 16 and significantly decreased during cancer progression." (PMID 30598639, 2018). "In addition, multi‐cancer invasive pathway and MAPK signal as well as Myc targets were downregulated in HOOK1 higher group, respectively in GSEA analysis in TCGA patient cohort and cell RNA‐seq analysis." (PMID 37085921, 2023).
tumor (7 papers, 2015 to 2024). "In fact, we observed that the decrease in HOOK1 sensitizes cells to compounds inducing ER stress and to proteasome inhibitors and that inhibiting HOOK1 prevented tumor formation in mouse models." (PMID 38807192, 2024). "Mechanistically, HOOK1 inhibited tumor growth and metastasis via canonical and non‐canonical TGF‐β pathway, and inhibited RCC angiogenesis and sunitinib resistance via TNFSF13B/VEGF‐A signaling." (PMID 37085921, 2023). "Mechanistically, HOOK1 inhibits tumor growth and metastasis via canonical TGF‐β/ALK5/p‐Smad3 and non‐canonical TGF‐β/MEK/ERK/c‐Myc pathway." (PMID 37085921, 2023). "Altogether, these data indicated that HOOK1 inhibited tumor growth and metastasis via canonical and non‐canonical TGF‐β pathway." (PMID 37085921, 2023). "It was found that HOOK1 overexpression could reduce the TNFSF13B transduced tumor burden and increased the sensitivity of RCC to sunitinib." (PMID 37085921, 2023). "Considering tumor microenvironment (TME) was a complex ecosystem and associated with response to checkpoint inhibitor therapy, we then evaluated whether HOOK1 could reprogram TME." (PMID 37085921, 2023). "Consistent with the in vitro effects, the enhanced tumor cell growth and weight after HOOK1 knockdown could be rescued in vivo by the addition of galunisertib." (PMID 37085921, 2023). "Together, these data corroborated our hypothesis that HOOK1 could drive tumor cells into a less mesenchymal phenotype and enhanced anti‐PD‐1 antitumor activity via TME remodeling." (PMID 37085921, 2023). "Tumor volumes and weights were smaller in the HOOK1‐overexpressing group than the control group." (PMID 37085921, 2023). "In addition, galunisertib treatment notably reduced the lung metastasis nodes and weight resulted from depletion of HOOK1, thus prolonging survival in tumor‐bearing nude mice." (PMID 37085921, 2023). "We first investigated HOOK1 mRNA mutations and/or copy loss in TCGA dataset, especially in ccRCC cohort, but not statistically significant when compared with other tumor types." (PMID 37085921, 2023). "Additionally, three paired independent samples were tested and found that HOOK1 protein levels showed a decreasing trend compared to matched adjacent non‐tumor tissue, primary tumor, and recurrence samples, which were all consistent with TCGA analysis results." (PMID 37085921, 2023). "The existence of a physical link for Ankyrin G and HOOK1 provide thus an additional clue to the hypothesized role of ANK3 in the regulation of EMT for tumor metastases." (PMID 26652480, 2015). "Moreover, we showed that HOOK1 could combine with anti‐PD‐1 therapeutics to enhance antitumor activity via tumor microenvironment remodeling." (PMID 37085921, 2023). "Interesting, levels of HOOK1 showed a negatively correlation with tumor PD‐L1, not PD‐1 expression in both cohorts, which were further demonstrated in meletin treated PDX tumors and murine RCC cell Renca induced tumors." (PMID 37085921, 2023). "By analyzing the RNA‐seq data and through multiple fundamental experiments, we confirmed HOOK1 inhibited the TGF‐β/ALK5/p‐Smad3 canonical signaling pathway and the noncanonical TGF‐β/MEK/ERK/c‐Myc signal, which contributed to suppress the tumor growth and metastasis in ccRCC." (PMID 37085921, 2023). "As TGF‐β was a well‐known regulator for tumor development, we investigated whether MAPK and Myc were potential downstream of HOOK1 via atypical TGF‐β signaling." (PMID 37085921, 2023).
infection (1 paper, 2018). The state of being infected such as from the introduction of a foreign agent such as serum, vaccine, antigenic substance or organism. "Further, a number of these CIE regulators, including Rab11a, Hook1, ACAP1/2, and EHD3, are targeted by microRNAs or downregulated by infection with HCMV." (PMID 30042195, 2018).
HOOK1 also shares sentences with these, for which no sentence is quoted: thyroid cancer (2 papers); asthma (1); astrocytoma (1); Azoospermia (1); cervical cancer (1); gastric cancer (1); Hypertension (1); kidney damage (1); lung adenocarcinoma (1); lung carcinoma (1); male fertility (1); metanephric adenoma (1); neurological disorders (1); non-small cell lung carcinoma (1); oropharyngeal squamous cell carcinoma (1); Parkinson disease (1); prostate carcinoma (1); small cell lung carcinoma (1).